FUS (FUS RNA binding protein)
Diseases named in the same sentence as FUS in open-access papers (continued):
Sharing a sentence is not in itself a finding about the gene and the disease.
amyotrophic lateral sclerosis (continued). "FUS proteinopathy is present in a group of heterogeneous disorders, including amyotrophic lateral sclerosis (ALS-FUS) and frontotemporal lobar degeneration (FTLD-FUS), which are both characterized by the formation of inclusion bodies containing nuclear FUS." (PMID 31866807, 2019). "One of the experiments under study selected FUS, TAF15 and TARDBP (referred to as TDP43 in the reference), since they are known to be related to amyotrophic lateral sclerosis (ALS)." (PMID 31238884, 2019). "RNA-binding protein pathology now represents one of the best characterized pathologic features of amyotrophic lateral sclerosis (ALS) and frontotemporal lobar degeneration patients with TDP-43 or FUS pathology (FTLD-TDP and FTLD-FUS)." (PMID 22993125, 2012). "A key hallmark of major neurodegenerative disorders—including Alzheimer’s disease (AD), amyotrophic lateral sclerosis (ALS), frontotemporal dementia (FTD), synucleinopathies and prion diseases—is the intracellular accumulation of aggregated proteins such as MAPT, TDP43, FUS, PRNP and SNCA." (PMID 41278186, 2025). "For example, enoxacin treatment could promote survival of differentiated motor neurons in the context of Amyotrophic Lateral sclerosis (ALS) pathology, where growing evidence links DNA damage accumulation to FUS and TDP‐43 ALS phenotypes." (PMID 39333024, 2025). "These aggregates stem from reversible dynamic LLPS transitioning into irreversible clusters, such as α‐synuclein in Parkinson's disease (PD), tau in Alzheimer's disease (AD), fused in sarcoma (FUS), and TAR DNA‐binding protein 43 (TDP‐43) in amyotrophic lateral sclerosis (ALS)." (PMID 41268324, 2025). "Beyond traditional approaches in understanding amyotrophic lateral sclerosis (ALS), multiple recent studies in RNA-binding proteins (RBPs)—including transactive response DNA-binding protein (TDP-43) and fused in sarcoma (FUS)—have instigated an interest in their function and prion-like properties." (PMID 32422969, 2020). "Indeed, a protective role for UPF1 has already been shown in primary neuronal models of amyotrophic lateral sclerosis (ALS) and frontotemporal dementia (FTD) induced by overexpression of the RNA-binding proteins, TDP43 and FUS." (PMID 32616520, 2020). "The neuromuscular disorder amyotrophic lateral sclerosis (ALS) is characterized by protein inclusions formed by either TAR DNA-binding protein of 43 kDa (TDP-43), Cu/Zn superoxide dismutase (SOD1), or fused in sarcoma (FUS), in both upper and lower motor neurons." (PMID 31736708, 2019). "In the case of amyotrophic lateral sclerosis (ALS) and frontotemporal dementia (FTD), aggregates of two RNA-binding proteins (RBPs), the TAR DNA-binding protein of 43 kDa (TDP-43) and the fused in sarcoma (FUS) gene product, are found in the cytoplasm of affected neurons." (PMID 30486313, 2018). "Fused in Sarcoma (FUS) is a multifunctional RNA-/DNA-binding protein, which is involved in the pathogenesis of the neurodegenerative disorders amyotrophic lateral sclerosis (ALS) and frontotemporal dementia (FTD)." (PMID 26834559, 2015). "For example, in amyotrophic lateral sclerosis (ALS) and frontotemporal dementia (FTD), changes in the localization of transactive responsive-DNA binding protein 43 (TDP-43) and fused in sarcoma (FUS), as well as formation of inclusion bodies containing these proteins are seen in neurons." (PMID 34194300, 2021). "For example, numerous genetic suppressors of FUS and TDP-43 toxicity, which are connected with amyotrophic lateral sclerosis and frontotemporal dementia, rescue toxicity without affecting FUS or TDP-43 aggregation in yeast." (PMID 24039611, 2013). "Amyotrophic lateral sclerosis (ALS), which appears to spread through the neuroaxis in a spatiotemporally restricted manner, is linked to heritable mutations in genes encoding SOD1, TDP-43, FUS, C9ORF72, or can occur sporadically without recognized genetic mutations." (PMID 26926802, 2016).
frontotemporal dementia (245 papers, 2011 to 2026). Frontotemporal dementia (FTD) comprises a group of neurodegenerative disorders, characterized by progressive changes in behavior, executive dysfunction and language impairment, as a result of degeneration of the medial prefrontal and frontoinsular cortices. "Additional ASO therapies are under investigation for other genetically defined forms of ALS, such as those involving FUS and C9orf72 mutations, and are also being explored in Huntington’s disease, Alzheimer’s disease, and frontotemporal dementia." (PMID 40869897, 2025). "Aggregates with extended intrinsically disordered areas of the Transactive response DNA-binding protein 43 (TDP-43) and Fused in sarcoma (FUS) proteins are associated with frontotemporal dementia and ALS." (PMID 41303502, 2025). "Atypical frontotemporal lobar degeneration with ubiquitin-positive inclusions (aFTLD-U) is a relatively rare cause of FTD characterized by FUS-positive inclusions, and is the underlying pathology in about 5% of all bvFTD cases." (PMID 34389969, 2021). "Mutations in the human FUS locus cause both frontotemporal dementia (FTD), and are associated with a small percentage of ALS cases." (PMID 30126171, 2018). "Several FUS mutations have been reported to be linked to familial ALS with features of frontotemporal dementia, and juvenile-onset ALS with cognitive impairment." (PMID 28928015, 2017). "Previous studies have shown increased FUS expression in patients affected by frontotemporal lobar degeneration associated with FUS (FTLD-FUS)." (PMID 27225265, 2016). "Here, we identified three cases of the behavioral variant of frontotemporal dementia (bvFTD) that display chorea with fused in sarcoma (FUS)-positive inclusions (FTLD-FUS) and the basophilic inclusion body disease (BIBD) subtype." (PMID 27044537, 2016). "Mutations in TARDBP (coding for TDP-43) and FUS are described in ALS patients with a family history but also in patients with fronto-temporal dementia (FTD) with a high risk (around 30%) to develop ALS." (PMID 25653590, 2014). "Additionally, FUS is a multifunctional DNA/RNA binding protein, and this gene is associated with familial amyotrophic lateral sclerosis/frontotemporal dementia." (PMID 33670352, 2021). "Furthermore, TDP-43–positive inclusions are found in most sporadic ALS patients, and inclusions containing either TDP-43 or FUS are a pathological hallmark in ∼45% and ∼10% of patients with frontotemporal dementia (FTD), respectively." (PMID 30209068, 2018). "This knowledge could also yield avenues for therapeutic intervention in diseases associated with aberrant assembly of these proteins, such as FUS-associated ALS (fALS-FUS) and frontotemporal lobar degeneration (FTLD-FUS)." (PMID 29677515, 2018). "FUS, a DNA/RNA binding protein, has been associated with amyotrophic lateral sclerosis and frontotemporal dementia (FTD) that present not only prominent degeneration of motor neurons but also deficits in social behaviors." (PMID 39056071, 2024). "Additionally, disrupted interactions between SFPQ/PSF and fused in sarcoma (FUS) has been shown in post mortem frontotemporal lobar degeneration (FTLD) brains and were associated with increased 4-repeat tau (4R-T) to 3-repeat tau (3R-T) ratios and underlying FTLD phenotype development." (PMID 35563596, 2022). "Patients with ALS and FUS mutations may also develop frontotemporal dementia (FTD)." (PMID 33071739, 2020). "FUS is a DNA/RNA binding protein linked to ALS as well as to frontotemporal dementia (FTD), another neurodegenerative disorder belonging to the same disease spectrum as ALS." (PMID 31277703, 2019). "It was also found that transgenic mice overexpressing fused in sarcoma (FUS), a marker associated with FUS-related ALS and frontotemporal dementia, exhibited mitochondrial anomalies and disruptions in the NMJ." (PMID 39062745, 2024).
frontotemporal dementia (continued). "Various family studies have shown a significant pathophysiological and clinical overlap between ALS and frontotemporal dementia (FTD), especially in cases related to variants in the C9ORF72, TARDBP, FUS, and VCP genes." (PMID 39596609, 2024). "FUS was of particular interest because it regulates several steps in mRNA maturation, including transport to dendrites, and FUS mutations lead to dendritic retraction in motor neurons, leading to ALS and frontotemporal dementia 27,109–114." (PMID 38168440, 2023). "Compared to the human subjects, the mSOD1 model appears to more closely mimic the patient’s data, while FUS mutations are not only linked to ALS but also to frontotemporal dementia (FTD), as the FUS mutant mice appear to share phenotypes with FTD." (PMID 34059131, 2021). "Sporadic frontotemporal dementia (FTD) is neuropathologically associated with TDP-43, Tau or FUS protein pathology that each is considered the cause of the clinical symptoms." (PMID 33324928, 2020). "Aβ and tau proteins in AD; α-syn in PD; TAR DNA-binding protein 43 (TDP43), tau, or fused in sarcoma (FUS) proteins in frontotemporal dementia (FTD); and TDP43 in motor neuron disease exhibit some properties of the misfolded prion protein." (PMID 32204380, 2020). "Non-4RT FTLD comprised 46 patients with TAR DNA-binding protein 43 (TDP-43) pathology, 10 patients with three-repeat (3R)-tau pathology (Pick’s disease), and four patients with fused in sarcoma (FUS) protein pathology." (PMID 32914550, 2020). "Ubiquitin-positive FUS aggregates have been found in fALS and in specific cases of frontotemporal lobar degeneration." (PMID 23620769, 2013). "Multiple neurodegenerative diseases are characterized by the abnormal accumulation of FUS protein including various subtypes of frontotemporal lobar degeneration with FUS inclusions (FTLD-FUS)." (PMID 24027631, 2013). "For instance, recent evidence has linked EWSR1, another RBP very similar to FUS and TAF15, to frontotemporal lobar degeneration with ubiquitin-positive inclusions (FTLD-U)." (PMID 22919483, 2012). "FUS- and ubiquitin-positive inclusions are also found in a variant of frontotemporal lobar degeneration (FTLD), termed FTLD-FUS." (PMID 23049996, 2012). "Importantly, we detected 25 HLA epitopes derived from 15 genes associated with Alzheimer’s and related dementias such as Tau, PLD3 (Alzheimer’s disease), TDP-43, FUS (Frontotemporal dementia), and PARK7, VPS35 (Lewy Body dementia)." (PMID 40568088, 2025). "Cytoplasmic FUS misexpression may also cause sporadic ALS and cytoplasmic FUS aggregates have been observed in patients with frontotemporal dementia." (PMID 40180610, 2025). "It is currently understood that the neurodegenerative disease-related proteins, especially TDP-43 (ALS), amyloid beta and tau (Alzheimer's disease), α-synuclein (Parkinson's disease, PD), and FUS (frontotemporal dementia, FTD), partially show some characteristics of misfolding prion proteins." (PMID 38500677, 2024). "The overexpression of GSTO was shown to reduce the citoplasmatic accumulation of two proteins whose abnormal aggregations are characteristics of ALS and frontotemporal dementia, namely, the fused in sarcoma (FUS) DNA/RNA-binding protein and the Transactive response DNA-binding protein-43 (TDP-43)." (PMID 38339026, 2024). "FUS is an RNA-binding protein with regulatory functions in the nucleus that accumulates pathologically in the cytoplasm in 5–10% of frontotemporal lobar degeneration (FTLD) cases, whereas TDP-43 or tau-positive inclusions are associated with the majority of FTLD cases." (PMID 38573556, 2024). "The underlying pathology is termed frontotemporal lobar degeneration (FTLD) and consists of distinct underlying pathologies including aggregation of transactive response DNA-binding protein 43 (TDP-43), tau and fused-in-sarcoma (FUS)." (PMID 37597044, 2023).
frontotemporal dementia (continued). "Furthermore, the methylation, phosphorylation, and acetylation of FUS or TDP-43 associated with ALS and frontotemporal dementia (FTD) decrease aggregation." (PMID 35805146, 2022). "FUS is causally associated with oncogenesis and neurodegeneration, and the FUS protein has been identified as a major component of intracellular inclusions in neurodegenerative disorders, including ALS and frontotemporal lobar degeneration." (PMID 35308095, 2022). "Furthermore, in this study, atrophy in the putamen was more marked than in the caudate in most groups (apart from FUS): Pick’s disease (38% difference from controls), FUS (33%), FTDP-17 (25%), CBD (24%), TDP-43 type A (25%) and TDP-43 type C (19%)." (PMID 34458729, 2021). "However, there is also significant involvement in those with Pick’s disease (45% difference from controls), more so than those with FUS (37%), TDP-43 type A (25%) or CBD (20%) pathology." (PMID 34458729, 2021). "Besides FUS-ALS, FUS mutations have been associated with other neurodegenerative diseases, such as frontotemporal dementia, chorea, mental retardation, psychosis and essential tremor." (PMID 34488813, 2021). "Mutations in FUS are causative of ALS and frontotemporal dementia (FTD)." (PMID 30344044, 2018). "Similarly, in frontotemporal lobar degeneration (FTLD) with FUS inclusions, TAF15 co-localized with FUS in those inclusions." (PMID 30081499, 2018). "With up to 5% of familial ALS attributable to FUS gene mutations, dominant or recessive inheritance, and identification in individuals with sporadic ALS and ALS with Parkinsonism or frontotemporal dementia, FUS has emerged as a significant genetic factor in the ALS landscape." (PMID 28634552, 2017). "Mutations in FUS are found in both familial and sporadic ALS, as well as in patients with ALS and frontotemporal dementia (FTD), and in frontotemporal lobar degeneration (FTLD) patients without motor impairment, suggesting a pathogenic overlap between ALS and other neurodegenerative diseases." (PMID 22272119, 2011). "In addition, non-mutated FUS is a constituent component of protein inclusions in approximately 5-10% of cases of frontotemporal lobar degeneration (FTLD)." (PMID 41832182, 2026). "For instance, in many cases of ALS and frontotemporal dementia (FTD), RBPs such as FUS and TDP43 are increasingly mislocalized to the cytoplasm, where they can aggregate." (PMID 40970514, 2025). "ALS is associated with several genes, for example, C9ORF72, TARDBP, SOD1 and FUS, with some genes also contributing to the presence of frontotemporal dementia (FTD)." (PMID 33094283, 2020). "TDP-43 and FUS are two proteins that are pathologically linked to ALS and frontotemporal dementia (FTD)." (PMID 32626703, 2020). "In analogy, prion-like assembly is a functional aspect of RNA-binding protein FUS, a 53 kDa protein with an aggregation propensity that is typically linked to the occurrence of unsoluble protein inclusions in amyotrophic lateral clerosis (ALS) and frontotemporal dementia (FTD; Shelkovnikova, 2013)." (PMID 25741240, 2015). "The three main types of frontotemporal lobar degeneration (FTLD) are characterized by the accumulation of abnormal proteins, namely tau, TDP-43 and FUS." (PMID 40207209, 2025). "TDP-43 and FUS aggregates are commonly observed in neurons of patients with ALS and frontotemporal dementia (FTD)." (PMID 39082979, 2024). "The two major proteins that aggregate in the frontotemporal dementia (FTD) are Tau and TDP-43, whereas a minority of patients aggregate FET proteins and the FUS protein." (PMID 39596513, 2024). "This is the case, for example, for the frontotemporal lobar degenerations (FTLD), that includes among others the FTLD-TDP, with the presence and aggregation of p-TDP-43 protein, and the FTLD-FUS with the fused in sarcoma (FUS) protein accumulation." (PMID 37065464, 2023).
frontotemporal dementia (continued). "In concrete subtypes of ALS and frontotemporal lobar degeneration (FTLD), called ALS-FUS and FTLD-FUS, cytoplasmic and nuclear inclusions of FUS are the characteristic features." (PMID 37759656, 2023). "Mutations in a number of different genes, including C9ORF72, TDP43, FUS and SOD1, can all lead to some form of motor neuron disorder or the related cognitive disorder frontotemporal dementia." (PMID 37671010, 2023). "The RNA/DNA-binding proteins FUS (also known as TLS) is also known to link to familial ALS and frontotemporal dementia (FTD), such as TDP-43." (PMID 35765969, 2022). "Several RNA-binding proteins of SGs including FUS, hnRNPA1, and TDP43 are meanwhile prone to undergo amyloid aggregation, which is closely associated with neurodegenerative diseases such as ALS and frontotemporal dementia (FTD)." (PMID 35384603, 2022). "Frontotemporal dementia (FTD), another major dementia, is typified by early-onset and by several protein inclusions such as tau, ubiquitin, Fused-in-Sarcoma (FUS) and TAR DNA-binding protein 43 (TDP-43)." (PMID 35159272, 2022). "Frontotemporal lobar degeneration (FTLD) represents a heterogeneous group of neurodegenerative disorders that are characterized by aggregates of different proteins such as TDP-43 and FUS." (PMID 34066951, 2021). "The neuropathological correlate of FTD is frontotemporal lobar degeneration (FTLD), characterized by tau-, TDP-43-, and FUS-immunoreactive neuronal inclusions." (PMID 30774737, 2019). "Of particular interest here, mutations in the highly conserved NLS region of the FUS gene, which encodes a protein that is involved in RNA transcription and processing, have been described in ALS and in ALS with frontotemporal dementia (ALS/FTD)." (PMID 31383794, 2019). "Through the generation of humanized FUS mice expressing full-length human FUS, we identify that when expressed at near endogenous murine FUS levels, both wild-type and ALS-causing and frontotemporal dementia (FTD)-causing mutations complement the essential function(s) of murine FUS." (PMID 30344044, 2018). "FUS proteinopathy defines the majority of tau- and TDP-43-negative cases of frontotemporal dementia." (PMID 28928015, 2017). "Building on recent genetic discoveries, Julie Snowden (University of Manchester, UK) showed the relationship between the diverse clinical characteristics and the underlying pathologies of frontotemporal dementia (FTD) (tau, TDP-43 and FUS) and associated genetic mutations (MAPT, C9orf72 and GRN)." (PMID 27391874, 2015). "FUS-positive inclusions have been detected in non-SOD1 ALS patient specimens, frontotemporal lobar degeneration, and neuronal intermediate filament inclusion disease." (PMID 23620769, 2013). "Similarly, PD is hallmarked by α-synuclein inclusions, ALS by TDP-43 and FUS aggregation, and frontotemporal dementia with tau, TDP-43 and FUS aggregates." (PMID 38845026, 2024). "PKA-mediated Rpn6 phosphorylation was found to induce an increase in proteasome activity and stimulate the degradation of aggregation-prone proteins such as tau, TDP-43, and FUS (fused in sarcoma), an RNA binding protein involved in ALS and frontotemporal dementia (FTD)." (PMID 37759569, 2023). "Cytoplasmic mislocalization of FUS also occurs in the absence of disease-associated mutations, both in ALS cases caused by other genetic determinants and in cases of frontotemporal lobar degeneration." (PMID 34290090, 2021). "There is increasing evidence that other neurodegenerative diseases, most notably Alzheimer’s disease (Aβ and tau), Parkinson’s disease (α‐synuclein), frontotemporal dementia (TDP43, tau or FUS) and motor neurone disease (TDP43), exhibit at least some of the misfolded prion protein properties." (PMID 31868945, 2020).